PKNOX1 (PBX/knotted 1 homeobox 1)
Diseases named in the same sentence as PKNOX1 in open-access papers (continued):
Sharing a sentence is not in itself a finding about the gene and the disease.
cancer (8 papers, 2012 to 2025). A tumor composed of atypical neoplastic, often pleomorphic cells that invade other tissues. "The TCGA and GTEx databases were used to evaluate the differential expression of PKNOX1 pan-cancer, and PKNOX1 gene mutation information was obtained from the cBioPortal and GSCALite platforms." (PMID 40625743, 2025). "The expression patterns and genetic mutation characteristics of PKNOX1 in a human pan-cancer dataset were comprehensively explored, and the relationships between PKNOX1 and pan-cancer survival prognosis and clinical pathology were analysed." (PMID 40625743, 2025). "This study analysed the correlations between PKNOX1 and immune infiltration and immune cells in pan-cancer TME." (PMID 40625743, 2025). "To investigate the genetic variation in PKNOX1 in pan-cancer, we used the cBioPortal and GSCALite online analysis webpages to analyse the genetic variation frequency, mutation type, and degree of DNA methylation." (PMID 40625743, 2025). "In this study, we analysed the expression pattern of PKNOX1 in pan-cancer via the TCGA and GTEx databases." (PMID 40625743, 2025). "Cox regression and Kaplan-Meier analyses were used to evaluate the value of PKNOX1 in pan-cancer prognosis." (PMID 40625743, 2025). "The enriched KEGG pathways indicated that PKNOX1 is involved in cancer-promoting processes such as cell-cell adhesion, the cell cycle and cell proliferation and deterioration signalling pathways." (PMID 40625743, 2025). "In subsequent studies, further exploration of the detailed cancer-promoting mechanism of PKNOX1 is necessary." (PMID 40625743, 2025). "In general, this study is the first to investigate PKNOX1 in pan-cancer, and elaborates on the relevant functions of PKNOX1 at multiple levels, such as expression, gene mutation, DNA modification, survival prognosis, immune analysis, and enrichment analysis." (PMID 40625743, 2025). "The expression pattern and biological function of PKNOX1 in pan-cancer were elucidated from multiple dimensions, highlighting the potential of PKNOX1 as a pan-cancer prognostic and immune marker, and exploring the potential mechanism of PKNOX1 in the occurrence and development of pan-cancer." (PMID 40625743, 2025). "Our study is the first to use the TCGA and GTEx databases to perform pan-cancer analysis of PKNOX1." (PMID 40625743, 2025). "Moreover, high expression of PKNOX1 is closely associated with poor prognosis in other pan-cancers, suggesting that PKNOX1 is a promising pan-cancer prognostic biomarker." (PMID 40625743, 2025). "Therefore, the use of a pan-cancer database to further study the regulatory function of PKNOX1 in tumors and the molecular mechanism of occurrence and development are highly important." (PMID 40625743, 2025). "Thus, PKNOX1 may be an effective prognostic marker for cancers." (PMID 40625743, 2025).
infection (2 papers, 2016 to 2022). The state of being infected such as from the introduction of a foreign agent such as serum, vaccine, antigenic substance or organism. "miR-19b-3p regulates inflammation and infection by targeting many targets, including granzyme B, an activator of signaling and transcription 3, and PKNOX1." (PMID 35812737, 2022).
peripheral neuropathy (2 papers, 2023 to 2025). A disorder affecting the peripheral nervous system. "For example, single nucleotide polymorphisms (SNPs) in the PKNOX1 gene are not only associated with an increased risk of painful peripheral neuropathy, but may also influence BIPN by regulating the transcription of the pain biomarker monocyte chemoattractant protein-1." (PMID 41383460, 2025).
PKNOX1 also shares sentences with these, for which no sentence is quoted: metabolic disease (4 papers); type 2 diabetes (4); Insulin resistance (3); Obesity (2); acute lymphoblastic leukemia (1); adrenocortical cancer (1); AIDS (1); anemia (1); B-cell lymphomas (1); breast invasive carcinoma (1); cervical cancer (1); cholangiocarcinoma (1); clear cell carcinoma (1); colorectal cancer (1); cyst (1); dementia (1); depression (1); diffuse large B-cell lymphoma (1); endothelial dysfunction (1); esophageal adenocarcinoma (1); esophageal carcinoma (1); gastric cancer (1); glioblastoma multiforme (1); glioma (1); head and neck squamous cell carcinoma (1); intestinal cancer (1); kidney stones (1); liver cancer (1); lung adenocarcinoma (1); lymphoma (1).
A further 21 diseases each share a sentence with PKNOX1 in 1 paper.